CAP1 (cyclase associated actin cytoskeleton regulatory protein 1)
Diseases named in the same sentence as CAP1 in open-access papers (continued):
Sharing a sentence is not in itself a finding about the gene and the disease.
breast carcinoma (continued). "In summary, we unravel cell context-dependent functions for CAP1 in the invasiveness of breast cancer cells." (PMID 27173014, 2016). "In metastatic breast cancer cells, depletion of CAP1 stimulated both the invasiveness and cell proliferation, while in non-metastatic MCF-7 cancer cells it actually had opposite effects." (PMID 27173014, 2016). "The findings help clarify some of the confusions surrounding the controversial roles of CAP1 in breast cancer and human cancers as a whole." (PMID 27173014, 2016). "Studies have demonstrated that CAP1 is overexpressed in hepatocelluar carcinoma, breast cancer, lung cancer and esophageal squamous cell carcinoma." (PMID 25652936, 2015). "It has been reported that the knockdown of the expression of CAP1 affects the breast cancer cell cycle, inhibiting the growth of breast cancer cancer." (PMID 25652936, 2015). "Indeed, CAP1 was reported to circulate in the plasma of metastatic cancer patients and in mouse models of breast cancer." (PMID 36566984, 2022). "The aim of this study was to investigate the impact of CAP1 and obesity on breast cancer cell proliferation, cell cycle distribution, and protein phosphorylation patterns to gain a better understanding of how adipokines affect breast cancer cells." (PMID 33738261, 2021). "Among assessed phosphoproteins altered ≥1.25-fold, 12 were uniquely modulated in CAP1 expressing, but not in CAP1 silenced cells, suggesting their potential involvement in CAP1-associated response to adipocyte stimulation in breast cancer cells." (PMID 33738261, 2021). "CAP1 silencing further impacted on the adipocyte-induced protein phosphorylation profiles, suggesting a potential role in the molecular mechanisms of obesity-related breast cancer." (PMID 33738261, 2021). "CAP1 down-regulation impairs cells migration in hepatocellular carcinoma cells, in esophageal squamous cell carcinoma, in breast cancer cells and in glioma cells." (PMID 33072768, 2020). "It was similar to our results but we separated different subtypes of breast cancer patients based on their clinical pathohistological diagnosis, and we could further considered BMI variable and metastatic gene CAP1 in our future study." (PMID 32226495, 2020). "The association of body constitution and breast cancer outcome is complex, and CAP1 is not working in isolation." (PMID 32560703, 2020). "Moreover, Resistin increases breast cancer metastasis potential through induction epithelial to mesenchymal transition, a process in which cancer cells lose their epithelial characteristics and gain mesenchymal-like features, and that these effects may be associated with CAP1." (PMID 33072768, 2020). "Resistin is among the top modulated adipokines secreted by adipocytes under obesity-associated metabolic conditions and therefore represents a plausible soluble mediator in the link between obesity, metabolic complications and breast cancer via the binding to CAP1." (PMID 33072768, 2020). "Firstly, more complex roles for CAP1 in cell migration and invasiveness that also involve cancer cell adhesion have led to a new concept of how CAP1 may control the invasiveness of breast cancer." (PMID 31151140, 2019). "Finally, we will discuss the relevance of these novel mechanistic insights to ultimately realizing the translational potential of CAP1 in targeted therapeutics for breast cancer." (PMID 31151140, 2019). "Moreover, CAP1 was also found to control proliferation in breast cancer cells, through the regulation of ERK (External signal-Regulated Kinase)." (PMID 31151140, 2019). "Unlike the increased cell size in the CAP1-knockdown HeLa and metastatic breast cancer cells, depletion of CAP1 did not cause noticeable increase in the size of PANC-1 or AsPC-1 cells." (PMID 30894654, 2019).
breast carcinoma (continued). "Using two shRNA constructs S2 and S3 that target independent nucleotide sequences and effectively silenced CAP1 in HeLa and breast cancer cells, we were able to generate stable clones with efficient CAP1 knockdown in the PANC-1 and AsPC-1 cells, as confirmed in Western blotting." (PMID 30894654, 2019). "The fact that the depletion of CAP1 led to altered ERK activity suggests that CAP1 may actually play a role in the proliferation of breast cancer cells, which promoted us to test it." (PMID 31151140, 2019). "As a result, in the CAP1-knockdown HeLa and the metastatic breast cancer cells, the positive effect from FAK activation is believed to have overcome the negative effect on cell motility and invasion due to the compromised actin filament turnover from loss of CAP1 function." (PMID 30894654, 2019). "Furthermore, we revealed a highly dynamic regulation of CAP1 expression levels in breast cancer cells, responding to cell culture conditions including serum starvation and stimulation." (PMID 30894654, 2019). "The cell context-dependent roles for CAP1 in breast cancer suggests that developing a targeting strategy tailored for the specific subtype of breast cancer can be critical in order to achieve desired treatment outcomes in targeting CAP1 or related cell signals in the treatment of breast cancer." (PMID 31151140, 2019). "Next we wanted to evaluate the impact of CAP1 tumor expression on breast cancer outcomes." (PMID 30524378, 2018). "Yet, the impact by resistin and in particular CAP1 on breast cancer remains elusive." (PMID 30524378, 2018). "Having shown the subtype-specific CAP1 expression in breast cancer cell lines, we sought to translationally link the experimental findings to primary human tumors by exploring gene expression data from 1,881 breast cancer patients using the GOBO platform." (PMID 30524378, 2018). "CAP1 may play a potential oncogenic role in pancreatic cancer and tumor suppressor in breast cancer." (PMID 28423713, 2017). "However, depletion of CAP1 in HeLa cells and breast cancer cells substantially stimulates the migration and invasion." (PMID 28423713, 2017). "We looked into potential changes in the focal adhesions in the CAP1 knockdown breast cancer cells." (PMID 27173014, 2016). "In breast cancer, ~10% of tested cancer samples had strong CAP1 staining." (PMID 27173014, 2016). "Thus our results support that altered ERK activity, but not cancer cell apoptosis, was responsible for the effects of CAP1 knockdown on cell proliferation and anchorage-independent colony formation in breast cancer cells." (PMID 27173014, 2016). "We tested how CAP1 depletion may have impacted these actin cytoskeletal structures in the different breast cancer cells." (PMID 27173014, 2016). "These mechanistic insights may ultimately lead to therapeutic strategies targeting CAP1 or its peripheral cell signals in breast cancer treatment." (PMID 27173014, 2016). "Moreover, phosphorylation at the regulatory site on CAP1 by upstream cell signals likely regulates CAP1 functions in both the proliferative transformation and the metastatic potential of breast cancer cells." (PMID 27173014, 2016). "These novel mechanistic insights may ultimately open up avenues for strategies targeting CAP1 in the treatment of breast cancer, tailored for specific types of the highly diverse disease." (PMID 27173014, 2016). "It has been reported that CAP1 is upregulated in breast cancer." (PMID 25652936, 2015). "Thus, the role of CAP1 in breast cancer is still controversial." (PMID 33738261, 2021). "Studies on CAP1 in our group over the last several years have led to the identification of a new cellular function for the protein in cell adhesion, its very first regulation mechanism through phosphorylation, as well as the profound and complex roles in the key functions of breast cancer cells." (PMID 31151140, 2019).
breast carcinoma (continued). "Importantly, our follow-up study supports the conservation of this functional interaction between CAP1 and FAK in breast cancer cells, where CAP1 actually fulfills more complex roles in regulating FAK, and cell adhesion and invasiveness, depending on the cell type." (PMID 31151140, 2019). "Activation of FAK caused by CAP1 depletion in HeLa and metastatic breast cancer cells is believed to have overcome the negative effect from the reduced actin filament turnover on cell motility; as a result, knockdown of CAP1 actually stimulates cell motility and invasiveness." (PMID 30894654, 2019). "Separate analyzes using the independent TCGA 1,105-sample breast cancer data set showed a positive correlation between the CAP1 mRNA expression and protein levels (Pearson's r = 0.36), while only a weak positive correlation between CAP1 and resistin (RETN) tumor expression (Pearson's r = 0.16)." (PMID 30524378, 2018). "Similarly, CAP1 knock down reduced both breast cancer cell proliferation and migration." (PMID 30524378, 2018). "Thus, depletion of CAP1 caused opposing effects in the metastatic and non-metastatic breast cancer cells on cell migration and invasion." (PMID 27173014, 2016). "Along with the mechanistic insights, identification of the cell context-dependent functions for CAP1 in breast cancer cells may help ultimately develop effective strategies targeting CAP1 in the treatment of breast cancer, that are tailored for sub-types of the highly diverse disease." (PMID 27173014, 2016). "Among the 718 breast cancer patients with tumor tissue included in the TMA, CAP1 expression was assessable in 669 tumors, of which 106 tumors (15.8%) displayed a low, 273 (40.8%) moderate, and 290 (43.3%) high CAP1 expression." (PMID 32560703, 2020). "Kaplan-Meier and multivariable Cox proportional hazard models were used to assess survival differences in terms of breast cancer-specific survival (BCSS) and overall survival (OS) according to body composition and CAP1 expression." (PMID 32560703, 2020). "Furthermore, high CAP1 expression was associated with poor tumor characteristics and correlated with expression of genes and biological pathways within growth promoting (such as Abl, RRAGC and mTOR) and cell motility processes (e.g., Arp2/3 complex, ARSB and FN1) in breast cancer." (PMID 30524378, 2018). "The third identified gene, CAP1, is an actin-regulating protein which has been shown to promote tumor growth and migration of solid cancers such as HCC, glioma, or breast cancer." (PMID 27585840, 2016). "Twelve of the phosphoproteins altered ≥1.25-fold by adipocyte stimulation from obese-like relative to normal conditions, were uniquely changed in CAP1 expressing, but not in CAP1 silenced breast cancer cells." (PMID 33738261, 2021). "In contrast, knockdown of CAP1 in non-metastatic MCF-7 breast cancer cells actually led to reduced FAK activity and compromised cell adhesion." (PMID 30894654, 2019). "Therefore, in addition to its traditionally focused roles in the actin cytoskeleton and cancer cell invasiveness, CAP1 also regulates cancer cell proliferation through ERK, at least in breast cancer." (PMID 31151140, 2019). "Alterations in the activities of FAK (Focal Adhesion Kinase) and ERK from CAP1 depletion that are consistent to the opposite adhesion and proliferation phenotypes were detected in the metastatic and non-metastatic breast cancer cells." (PMID 31151140, 2019). "Lastly, we also detected the elevated activity of ERK in the CAP1-knockdown metastatic breast cancer cells, while reduced ERK activity was detected in the non-metastatic cancer cells." (PMID 31151140, 2019). "How the depletion of CAP1 led to the opposing phenotypes in the actin cytoskeleton and focal adhesions in metastatic and non-metastatic breast cancer cells remains to be elucidated." (PMID 27173014, 2016). "We identify opposing roles for CAP1 in the invasiveness of metastatic and non-metastatic breast cancer cells." (PMID 27173014, 2016).
breast carcinoma (continued). "Taken together, our above results neither support up-regulation of CAP1 in breast cancer cells, nor any correlation between CAP1 expression levels and the grade of invasiveness of a cancer cell type." (PMID 27173014, 2016). "In summary, alterations in the actin cytoskeleton, cancer cell adhesion and invasiveness consistently support cell context-dependent functions for CAP1 in regulating cancer cell invasiveness in the metastatic and non-metastatic breast cancer cells." (PMID 27173014, 2016). "We identify opposite functions for CAP1 in both the metastatic potential and proliferation of metastatic and non-metastatic breast cancer cells." (PMID 27173014, 2016). "The data show that all the breast cancer cell lines express varying levels of IL-6, CAP1 and IL-6R, whereas no expression of resistin is observed either at the protein or transcript level in any of the cell lines (data not shown)." (PMID 25868978, 2015). "Other breast cancer treatment modalities were not related to CAP1 tumor expression." (PMID 32560703, 2020). "Indeed, we detected cell proliferation phenotypes that were consistent with the altered ERK activity in both the CAP1-knockdown metastatic and non-metastatic breast cancer cells." (PMID 31151140, 2019). "However, in either case, it is intriguing how the depletion of CAP1 in the metastatic and non-metastatic breast cancer cells can actually exert opposite effects on FAK activity and cell adhesion." (PMID 31151140, 2019). "However, a separate study suggested that CAP1 exert distinct functions dependent on breast cancer subtype, as CAP1 depletion in highly invasive MDA-MB-231 cells stimulated proliferation and migration, contrary to ER+ MCF-7 cells where CAP1 knock down inhibited migration." (PMID 30524378, 2018). "Since CAP1 depletion led to altered activity of ERK, a key regulator of cell proliferation, we speculated that CAP1 may also regulate proliferative transformation in breast cancer cells." (PMID 27173014, 2016). "Secondly, the phosphor-regulation mechanism of CAP1, as well as the responsible phosphor-regulatory cell signals that are identified, may help to develop strategies for targeting CAP1 in breast cancer therapeutics without directly targeting the cytoskeletal protein." (PMID 31151140, 2019). "In addition, no up-regulation of CAP1 was detected in breast cancer cells." (PMID 30894654, 2019). "In the absence of adipocyte stimulation, CAP1 knockdown resulted in approximately 25 and 20% reduced proliferation of T47D and MDA-MB-231 breast cancer cells, respectively, in both normal and obese-like conditions (P<0.001)." (PMID 33738261, 2021). "Unlike the case in breast cancer cells, we did not detect alterations in ERK activity in the CAP1-knockdown cells." (PMID 30894654, 2019). "Depletion of CAP1 led to opposite alterations in FAK activity and phenotypes in the adhesion and invasiveness in the metastatic and non-metastatic breast cancer cells, with the metastatic cancer cells behaving similarly to HeLa cells." (PMID 31151140, 2019). "Similar to the case with effects on FAK activity derived from CAP1 depletion, opposite effects on ERK activity were detected in the metastatic and non-metastatic breast cancer cells, where elevated ERK activity in the metastatic breast cancer cells was detected along with activated FAK." (PMID 31151140, 2019).
pancreatic cancer (12 papers, 2009 to 2023). "CAP1 phosphorylated at S308/S310 regulatory site is associated with the increased activity of GSK-3β observed in pancreatic cancer." (PMID 36430630, 2022). "CAP1 was found upregulated in pancreatic cancer xenografts transplanted into immuno-deficient mice, and CAP1-positive tumor cells in clinical specimens correlated with the presence of lymph node metastasis and with the poor prognosis of patients." (PMID 33072768, 2020). "Considering that regulating the actin cytoskeleton is a key mechanism underlying the role of CAP1 in pancreatic cancer cell invasiveness, it is possible that CAP2 shares the role with CAP1 in regulating cancer cell invasiveness." (PMID 30894654, 2019). "CAP1 is implicated in pancreatic cancer, among a number of other malignancies, while its role remains to be better established along with underlying mechanisms." (PMID 30894654, 2019). "CAP1 (adenylate cyclase-associated protein 1) overexpressed in pancreatic cancers is involved in cancer cell motility." (PMID 20015385, 2009). "In addition to the effect of GSK-3β on proliferation and inhibition of apoptosis, GSK-3β phosphorylates/inhibits Cyclase-Associated Protein 1 (CAP-1), leading to increased migration and invasion of pancreatic cancer cells." (PMID 36430630, 2022). "Together, these results support that phosphor-regulation through the S308/S310 tandem site plays an important role for CAP1 to promote the motility and invasion of pancreatic cancer cells." (PMID 30894654, 2019). "Our findings support the notion that phosphor-regulation is of critical importance for CAP1 functions in the actin cytoskeleton and the invasiveness of pancreatic cancer cells." (PMID 30894654, 2019). "CAP1 is believed to promote pancreatic cancer cell invasiveness through both promoting actin filament turnover and controlling cell adhesion." (PMID 30894654, 2019). "We report here our findings that CAP1 is required for both the motility and invasion in pancreatic cancer cells." (PMID 30894654, 2019). "Our findings support that phosphor-regulation through S308/S310 is crucial for CAP1 to regulate the actin cytoskeleton and promote invasiveness in pancreatic cancer cells." (PMID 30894654, 2019). "We tested the effect of stable CAP1 knockdown on pancreatic cancer cell invasiveness, by conducting wound healing assays, Transwell migration assays as well as Matrigel invasion assays." (PMID 30894654, 2019). "In this study, we investigated roles for CAP1 and its phosphor-regulation in pancreatic cancer cells." (PMID 30894654, 2019). "Our results from CAP1 knockdown and re-expression reveal that CAP1 is indeed required for both the motility and invasion of pancreatic cancer cells." (PMID 30894654, 2019). "Taken together, these results support that phosphor-regulation through S308/S310 plays an important role for CAP1 to promote the motility and invasion in pancreatic cancer cells." (PMID 30894654, 2019). "In this study, we sought to further, and more systematically, determine roles for CAP1 and its phosphor-regulation in pancreatic cancer cells." (PMID 30894654, 2019). "In pancreatic cancer cells, depletion of CAP1 led to reduced FAK activity, and it is likely that the reduced cancer cell invasiveness caused by CAP1 knockdown derives from decreases in both actin filament turnover and cell adhesion." (PMID 30894654, 2019). "Our analysis revealed that CAP1 was over-expressed in bladder, lung, lymphoma, melanoma, head-neck, pancreatic cancers, but was under-expressed in breast and leukemia cancers as compared to that in normal tissue." (PMID 28423713, 2017). "For instance, our study indicated that CAP1 is highly expressed in lung cancer, elevated in pancreatic cancer." (PMID 28423713, 2017). "The co-expression profile of CAP1 was identified with a big cluster of 127 genes across 39 pancreatic carcinomas and 39 normal pancreatic tissues, as well as 52 genes across 32 head-neck and 26 normal samples." (PMID 28423713, 2017).